CFTR (CF transmembrane conductance regulator)
Diseases named in the same sentence as CFTR in open-access papers (continued):
Sharing a sentence is not in itself a finding about the gene and the disease.
cystic fibrosis (continued). "Cystic fibrosis which is a lethal autosomal recessive disorder caused by mutation of the CF transmembrane regulator (CFTR) gene, is characterized by an intense neutrophil-dominated airway inflammation and a chronic bacterial colonization with Pseudomonas aeruginosa." (PMID 23181059, 2012). "Given the previous association of 5-HTTLPR with PTSD, a role for rs169656258 as a modifier is consistent with a number of other disorders, most notably cystic fibrosis, a monogenic disease determined by mutations of the cystic fibrosis transmembrane conductance regulator (CFTR) gene." (PMID 21545724, 2011). "In cystic fibrosis, the most common mutation in cystic fibrosis transmembrane conductance regulator (CFTR) leads to its retention in the ER and degradation by the UPS; interfering with chaperone activity can prevent ER-sequestration, resulting in restored transport to the plasma membrane." (PMID 21695262, 2011). "Cystic fibrosis, caused by reduced CFTR function, includes severe sinonasal disease which may predispose to lung disease." (PMID 21935358, 2011). "For example, the gene CFTR, widely recognized as the cause of cystic fibrosis, has been consistently associated with pancreatitis, may be implicated in chronic rhinitis, and may play a protective role in gastrointestinal disorders." (PMID 20092628, 2010). "A classic example of a disease caused by protein mislocalization is cystic fibrosis which is caused by retention of the cystic fibrosis transmembrane conductance regulator (CFTR) protein in the endoplasmic reticulum, instead of its localizing to the cell surface." (PMID 20221251, 2010). "TGR5 function has so far not been investigated in PSC, but given the interaction with CFTR, it is interesting that cystic fibrosis (caused by CFTR mutations) may involve liver disease, often resembling PSC." (PMID 20811628, 2010). "The most common mutation in CFTR gene, the cystic fibrosis chloride channel, is F508; CFTR protein bearing this deletion has considerable residual activity but does not reach the cell membrane, being retained within the cells and routed for degradation because of the single missing amino acid." (PMID 20170480, 2010). "Cystic fibrosis is a debilitating lung disease due to mutations in the cystic fibrosis transmembrane conductance regulator protein (CFTR) and is associated with chronic infections resulting in elevated myeloperoxidase activity and generation of hypochlorous acid (HOCl)." (PMID 20799947, 2010). "Cystic fibrosis is caused by loss of function of the cAMP regulated anion channel CFTR." (PMID 20843337, 2010). "Patient ID136 has been diagnosed with cystic fibrosis due to mutations in the CFTR gene, microphthalmia, cleft palate, hemivertebrae, hemifacial hypoplasia, a ventriculoperitoneal shunt for hydrocephalus, talipes, growth hormone deficiency and a small pituitary gland." (PMID 21070663, 2010). "Mutations of CFTR gene have been associated with Cystic Fibrosis; however, the mechanism for its direct participation in the disease pathology remains unclear." (PMID 19335897, 2009). "CFTR is a polytopic plasma membrane chloride channel in which mutations cause cystic fibrosis." (PMID 19680550, 2009). "Deletion of phenylalanine at position 508 (ΔF508) in CFTR is the most common cystic fibrosis causing mutation, resulting in a temperature sensitive folding defect, retention of the protein in the endoplasmic reticulum (ER) and subsequent degradation by the proteasome." (PMID 19247502, 2009). "Deletion of Phe508 in CFTR NBD1 is the most frequent mutation in patients with cystic fibrosis." (PMID 18463704, 2008). "Cystic fibrosis, the most common lethal autosomal recessive genetic disease, is caused by mutations of the CF gene, which normally encodes the CF transmembrane conductance regulator (CFTR), a multifunctional cAMP-dependent Cl- channel in the apical membrane of secretory epithelial cells." (PMID 16938132, 2006).
cystic fibrosis (continued). "TRD has been seen for a) the transmission of disease alleles such as delta F508 of the CFTR gene for cystic fibrosis and b) the inheritance of the most common Robertsonian translocation, and is a phenomenon for which there is extensive evidence in the human genome." (PMID 16092963, 2005). "Cystic fibrosis is a severe genetic disorder that significantly impacts the respiratory and digestive systems, Cystic fibrosis is primarily caused by mutations in the cystic fibrosis transmembrane conductance regulator (CFTR) gene." (PMID 41579054, 2026). "Cystic fibrosis is a rare autosomal recessive genetic disease due to bi‐allelic pathogenic variants in the gene Cystic Fibrosis Transmembrane Conductance Regulator (CFTR), including F508del, the most common pathogenic variant." (PMID 41499328, 2026). "CFTR mutations that reduce channel activity cause cystic fibrosis, but clinically used modulator drugs that boost channel function can alleviate disease symptoms." (PMID 41920076, 2026). "Cystic fibrosis is an autosomal recessive disorder caused by pathogenic variants in the cystic fibrosis transmembrane conductance regulator (CFTR) gene and primarily affects the respiratory, digestive, and reproductive systems." (PMID 41898631, 2026). "The root cause of CF is mutations in the cystic fibrosis transmembrane conductance regulator (CFTR) gene, which impair epithelial chloride and bicarbonate secretion." (PMID 41486400, 2026). "Cystic fibrosis is caused by loss-of-function variants in the cystic fibrosis transmembrane conductance regulator (CFTR) chloride and bicarbonate channel and affects multiple organs, with pancreatic involvement showing very high penetrance." (PMID 41683706, 2026). "Cystic fibrosis is a monogenic disorder caused by mutations in the CFTR gene, which encodes a cAMP-regulated anion channel at the apical plasma membrane (PM) of epithelial cells." (PMID 41723327, 2026). "Cystic fibrosis is a congenital condition caused by mutations in the CF transmembrane conductance regulator (CFTR) gene." (PMID 41489009, 2026). "Cystic fibrosis is a rare, monogenic hereditary disorder caused by mutations in the CF transmembrane conductance regulator (CFTR) gene, which encodes the CFTR protein." (PMID 41503026, 2026). "Cystic fibrosis is a monogenetic disease caused by mutations in the plasma membrane anion-channel CF transmembrane conductance regulator (CFTR)." (PMID 41489009, 2026). "Cystic fibrosis is a life-limiting genetic disorder caused by deleterious variants in the CFTR gene that results in altered mucus impairing the airway epithelia." (PMID 42100873, 2026). "Cystic fibrosis is an autosomal recessive disorder caused by mutations in the CF transmembrane conductance regulator (CFTR)." (PMID 40980774, 2025). "Cystic fibrosis is a progressive disease caused by mutations in the CFTR gene leading to loss of CFTR anion channel function." (PMID 40909600, 2025). "Cystic fibrosis is characterized by chronic neutrophilic inflammation and progressive lung damage due to mutations in the CFTR gene." (PMID 41164170, 2025). "Using four hypothetical cases based on real-world data, we illustrate diverse clinical trajectories: diagnosis of cystic fibrosis, reclassification as a CFTR-related disorder (CFTR-RD), non-CF designation, and persistent diagnostic uncertainty." (PMID 40700044, 2025). "CF disease is the result of mutations in the cystic fibrosis transmembrane regulator (CFTR) gene that lead to a reduction in CFTR protein production or function." (PMID 40565059, 2025). "Cystic fibrosis is a common autosomal recessive disorder caused by mutations in the CF transmembrane conductance regulator (CFTR) gene, leading to dysfunctional CFTR protein and impaired chloride ion channels on epithelial cell membranes." (PMID 41359105, 2025).
cystic fibrosis (continued). "Cystic fibrosis is a genetic disorder primarily affecting the lungs and digestive system, caused by mutations in the CFTR gene encoding an epithelial chloride and bicarbonate channel." (PMID 41487515, 2025). "Cystic fibrosis is a recessive autosomal disease caused by dysfunction of the CF transmembrane conductance regulator (CFTR) channel." (PMID 39788554, 2025). "Cystic fibrosis is an autosomal recessive disease caused by mutations in the cystic fibrosis transmembrane conductance regulator (CFTR) gene, expressed on the apical surface of epithelial cells, which regulates ion transport through chloride channels." (PMID 40700326, 2025). "Cystic fibrosis is an autosomal recessive condition that is caused by pathogenic variants in the CF transmembrane conductance regulator (CFTR) gene." (PMID 41318507, 2025). "Cystic fibrosis is a rare genetic disease caused by mutations or errors in the Cystic Fibrosis Transmembrane Conductance Regulator (CFTR) gene." (PMID 40832610, 2025). "Loss-of-function CFTR gene mutations cause cystic fibrosis via various molecular mechanisms, including altered expression, trafficking, and/or activity of the CFTR chloride channel." (PMID 41373889, 2025). "Cystic fibrosis is an autosomal recessive disorder characterized by the deficiency or dysfunction of the CF transmembrane conductance regulator (CFTR)." (PMID 39865444, 2025). "These include people with mutations in the CFTR leading to cystic fibrosis, or pollution/smoke-induced lung damage leading to COPD." (PMID 40353451, 2025). "Cystic fibrosis is a progressive, multi-organ, genetic disease caused by dysfunctional CF transmembrane conductance regulator (CFTR)." (PMID 39935472, 2025). "In cystic fibrosis, most CFTR mutations cause partial (Class II) or complete (Class I) loss of function." (PMID 40832610, 2025). "Cystic fibrosis is a genetic disorder caused by variants in the CFTR gene, affecting multiple organ systems, including the lungs, pancreas, and digestive tract." (PMID 40468859, 2025). "Cystic Fibrosis is an autosomal recessive genetic disease, which courses with pathogenic variants of the CFTR (Cystic Fibrosis Transmembrane Regulator) gene, located on the long arm of chromosome 7." (PMID 40398368, 2025). "Cystic fibrosis is an autosomal recessive disorder resulting from variants in the cystic fibrosis transmembrane conductance regulator (CFTR) gene, which encodes a cAMP-regulated chloride channel protein." (PMID 40182926, 2025). "Mutations in CFTR, the gene that encodes CFTR, cause cystic fibrosis, a rare autosomal recessive disease that affects the lungs and digestive system." (PMID 40333927, 2025). "Cystic fibrosis is an autosomal recessive, multisystem disorder caused by mutations in the cystic fibrosis transmembrane conductance regulator (CFTR) gene, which disrupts ion and water transport across epithelial cells." (PMID 40426552, 2025). "Cystic fibrosis is a genetic disease due to mutations in the cystic fibrosis transmembrane conductance regulator (CFTR) gene." (PMID 40332143, 2025). "Cystic fibrosis is an autosomal recessive disease caused by mutations in the CF transmembrane conductance regulator (CFTR) gene with multi‐system effects including pulmonary, gastrointestinal, endocrinological, musculoskeletal and genitourinary." (PMID 40766167, 2025). "Cystic fibrosis is a severe hereditary disease that is inherited in an autosomal recessive manner and is caused by mutations in the CFTR gene." (PMID 40299508, 2025). "Cystic fibrosis is a genetic disorder caused by mutations in the CFTR gene, leading to multi-system impairment." (PMID 41465880, 2025). "Until recently, elexacaftor–tezacaftor–ivacaftor (ETI) was approved only for individuals with cystic fibrosis who carried at least one copy of the Phe508del mutation, the most common CFTR mutation in Caucasian populations." (PMID 40648998, 2025).
cystic fibrosis (continued). "Cystic fibrosis is a rare hereditary, life-limiting, multiorgan disease caused by mutations in the cystic fibrosis transmembrane conductance regulator (CFTR) gene that encodes a cAMP-regulated anion channel." (PMID 40261705, 2025). "Cystic fibrosis is an autosomal recessive inherited form of bronchiectasis caused by mutations in the cystic fibrosis transmembrane conductance regulator (CFTR) gene." (PMID 40718166, 2025). "Cystic fibrosis is an autosomal recessive genetic disease caused by mutations in the CF transmembrane conductance regulator (CFTR) gene on 7q31.2." (PMID 40933967, 2025). "For instance, in cystic fibrosis, precision medicine has revolutionized treatment through the identification of genetic mutations like F508del, enabling the development of targeted therapies such as cystic fibrosis transmembrane conductance regulator (CFTR) modulators." (PMID 39857751, 2025). "Cystic fibrosis is caused by homozygous mutations in the cystic fibrosis transmembrane conductance regulator (CFTR) gene, resulting in multi-organ dysfunction and decreased lifespan and quality of life." (PMID 40972653, 2025). "The CF is a genetic disorder resulting from mutations in the cystic fibrosis transmembrane conductance regulator (CFTR) gene, and is marked by airway mucus obstruction, chronic inflammation, and pulmonary fibrosis." (PMID 40740941, 2025). "For example, approximately 13% of mutations in the CF transmembrane conductance regulator (CFTR) gene, which is associated with cystic fibrosis, are categorized as "splicing mutations"." (PMID 39932919, 2025). "Cystic fibrosis is a hereditary disorder caused by mutations in the Cystic Fibrosis Transmembrane Conductance Regulator (CFTR) gene." (PMID 40433478, 2025). "Modulators of cystic fibrosis transmembrane conductance regulator (CFTR) mutated protein significantly improved the outcome of subjects with CF." (PMID 40724864, 2025). "Cystic fibrosis is an autosomal recessive disease caused by mutations in the CFTR gene, which encodes a cAMP-activated chloride channel essential for epithelial function." (PMID 41148816, 2025). "CF is a multi-organ disease caused by mutations in the gene encoding cystic fibrosis transmembrane conductance regulator (CFTR), an apical epithelial ion channel involved in chloride and bicarbonate transport." (PMID 40272253, 2025). "Cystic Fibrosis is an autosomal recessive hereditary disorder resulting from mutations in the CF Transmembrane Conductance Regulator (CFTR) gene, located on chromosome 7." (PMID 40723024, 2025). "Cystic fibrosis is an autosomal recessive inherited condition caused by mutations in the gene encoding cystic fibrosis transmembrane conductance regulator (CFTR)." (PMID 40237819, 2025). "In the context of CF, a disease characterised by pathogenic variants of the cystic fibrosis transmembrane conductance regulator (CFTR) gene, mouse models fail to exhibit CF‐like lung pathology." (PMID 39998270, 2025). "Cystic fibrosis is a rare, autosomal recessive disorder caused by variants in the CF transmembrane conductance regulator (CFTR) gene, resulting in defective ion transport across epithelial membranes." (PMID 41496868, 2025). "One common lung disease that likely initiates before birth is the inherited disorder CF, which is caused by mutations in the cystic fibrosis transmembrane conductance regulator (CFTR) gene." (PMID 40495135, 2025). "Logistic regression tested associations between CFTR carrier status and 11 cystic fibrosis ‐related phenotypes." (PMID 40468859, 2025). "Cystic fibrosis is a life-shortening multisystem disease resulting from mutations in the cystic fibrosis transmembrane conductance regulator (CFTR) gene, causing the most devastating phenotypes in the airway and pancreas." (PMID 40095037, 2025). "CF originates from mutations in the cystic fibrosis transmembrane conductance regulator (CFTR) gene, located on chromosome 7." (PMID 40868633, 2025).
cystic fibrosis (continued). "Background/Objectives: Cystic Fibrosis is an autosomal recessive genetic disorder caused by variants in the gene encoding the cystic fibrosis transmembrane conductance regulator (CFTR) protein." (PMID 40217771, 2025). "CF is a progressive, multisystem disorder that results from mutations in the cystic fibrosis transmembrane conductance regulator (CFTR) gene." (PMID 40807022, 2025). "Cystic Fibrosis, caused by mutations in the cystic fibrosis transmembrane conductance regulator (CFTR) gene, is a multi-organ disease that, in the current treatment era, most severely affects the lung." (PMID 40501816, 2025). "Cystic fibrosis, the most common hereditary lung disease in Caucasians, is caused by dysfunction of the cystic fibrosis transmembrane conductance regulator (CFTR)." (PMID 40806745, 2025). "Genetic mutations that yield a defective cystic fibrosis transmembrane regulator (CFTR) protein cause CF, a life-limiting autosomal-recessive Mendelian disorder." (PMID 41330381, 2025). "Classified as having “varying clinical consequences” (VVCC), it may produce a wide spectrum of CF phenotypes when combined in trans with a pathogenic variant on the other CFTR allele, ranging from asymptomatic cases to CFTR-related disorders (CFTR-RD) or classical cystic fibrosis." (PMID 40564735, 2025). "Around 90% of CF patients carry the ΔF508 mutation in the cystic fibrosis transmembrane conductance regulator (CFTR) gene, which results in the deletion of a phenylalanine residue at position 508 in the CFTR protein." (PMID 41323797, 2025). "Advancements in treatments for cystic fibrosis have been driven by identifying its genetic origin: mutations in the CFTR gene." (PMID 40227282, 2025). "Cystic fibrosis is an autosomal recessive multiorgan disease caused by mutations of the cystic fibrosis transmembrane conductance regulator (CFTR) gene, which leads to impaired CFTR channel function and compromised chloride and bicarbonate secretion." (PMID 40806025, 2025). "Cystic fibrosis is an autosomal recessive condition caused by mutations in the CF transmembrane conductance regulator (CFTR) gene, which encodes a chloride/bicarbonate channel expressed in airway, intestinal and exocrine tissues." (PMID 41439084, 2025). "CF is an autosomal recessive multi-organ disease, caused by mutations in the Cystic Fibrosis Transmembrane Conductance Regulator (CFTR) gene." (PMID 40981312, 2025). "The cystic fibrosis causing variant G542X harbours a premature translation stop signal in the cystic fibrosis transmembrane conductance regulator (CFTR) mRNA." (PMID 40192756, 2025). "Cystic fibrosis follows an autosomal recessive behavior of inheritance which can be characterized by the presence of mutations in the CFTR (cystic fibrosis transmembrane regulator) gene." (PMID 40910001, 2025). "Recent advances in CRISPR-based treatments for cystic fibrosis have shown promising results, primarily through base-editing approaches targeting the CFTR mutations that cause the disease." (PMID 41211267, 2025). "Cystic fibrosis is an autosomal-recessive disorder related to mutations of the CFTR gene that is responsible for the synthesis of an epithelial ionic channel." (PMID 40284567, 2025). "NTM infections are increasingly recognized in cystic fibrosis, where impaired phagocytosis and abnormal mucociliary function, often due to CFTR mutations like F508del, foster infection risk." (PMID 40430792, 2025). "Cystic fibrosis, caused by the dysfunction of the CF transmembrane regulator (CFTR) gene, is characterized by the build‐up of mucous in the airways leading to chronic lung infection and inflammation." (PMID 39285622, 2025). "CF is an autosomal recessive disease that is exhibited when both alleles of the cystic fibrosis transmembrane conductance regulator (CFTR) harbor mutations that result in improperly functioning and/or expressed proteins." (PMID 39859187, 2025).